CASR (calcium sensing receptor)
Diseases named in the same sentence as CASR in open-access papers (continued):
Sharing a sentence is not in itself a finding about the gene and the disease.
cholestasis (1 paper, 2020). Impairment of the bile flow caused by obstruction within the liver, or outside the liver in the bile duct system. "As mentioned in in vivo study, both the mitochondrial pathway and MAPK pathway are associated with cholestasis-related hepatocyte apoptosis caused by CaSR." (PMID 32180721, 2020). "We hypothesize that LDHJ regulates the expression of CaSR and subsequently regulates hepatocyte apoptosis caused by cholestasis." (PMID 32180721, 2020). "Based on these results, LDHJ granules inhibited the expression of CaSR in the young rats with ANIT-induced cholestasis." (PMID 32180721, 2020). "Based on the results from in vivo and in vitro studies, LDHJ functions as an antagonist of CaSR to regulate hepatocyte apoptosis in cholestasis through the mitochondrial pathway and mitogen-activated protein kinase pathway." (PMID 32180721, 2020). "Using the primary hepatocytes, we first investigated the molecular mechanism of CaSR-mediated hepatocyte apoptosis in cholestasis." (PMID 32180721, 2020). "In the present study, [Ca2+]i and ROS levels were initially detected to explore the more specific role of CaSR in the cholestasis-related hepatocyte apoptosis." (PMID 32180721, 2020). "Western blot analyses were performed to assess the effects of LDHJ granules on CaSR levels in the young rats with cholestasis." (PMID 32180721, 2020). "In the current study, we further confirm the protective effects of LDHJ on cholestasis-related hepatocyte apoptosis through downregulating of CaSR and participating in the mitochondrial pathway and MAPK pathway." (PMID 32180721, 2020). "All of them could ameliorate the intrahepatic cholestasis, as verified by the decreased levels of liver injury and cholestasis-related biomarkers, downregulate CaSR expression and inhibit hepatocyte apoptosis." (PMID 32180721, 2020). "Overall, these results testify the CaSR may be crucial in leading to cholestasis-related hepatocyte apoptosis." (PMID 32180721, 2020). "Therefore, CaSR may be crucial in leading to cholestasis-related hepatocyte apoptosis." (PMID 32180721, 2020). "Haematoxylin and eosin (HE) staining, biochemical assays, terminal deoxynucleotidyl transferase-mediated dUTP-biotin nick end labeling (TUNEL) method, and Western blot analyses were used to investigate the role of CaSR and the potential mechanisms of the effects of LDHJ on cholestasis." (PMID 32180721, 2020). "However, the mechanism by CaSR-mediated cholestasis-related hepatocyte apoptosis is not fully understood." (PMID 32180721, 2020).
Cognitive impairment (1 paper, 2020). Abnormal cognition is characterized by deficits in thinking, reasoning, or remembering. "In this study, molecular technology such as live-cell imaging combined with behavioral tests were used to explore the role and the underlying mechanism of CaSR in the cognitive deficits in AD mice." (PMID 32670047, 2020). "In order to study the single factor of Aβ and the underlying mechanism of CaSR in Aβ-mediated synaptic and cognitive impairment, the AD mouse model, made by microinjection with Aβ1–42 oligomers, were used in the rest of our study." (PMID 32670047, 2020). "As a promising therapeutic target, we therefore evaluated the role of CaSR in cognitive deficits in the mouse model of AD and its underlying cellular mechanisms." (PMID 32670047, 2020). "Inhibition or down-regulation of CaSR mediates Aβ-induced synapse formation and cognitive deficits partially, through the activation of the cPLA2/PGE2 pathway." (PMID 32670047, 2020). "Inhibition of CaSR with NPS 2143 prevented Aβ1–42-induced cognitive deficits in a dose-depended manner." (PMID 32670047, 2020). "cPLA2/PGE2 signaling pathways might be involved in the effects of CaSR on Aβ-induced cognitive impairment." (PMID 32670047, 2020). "Thus, CaSR mediates AD-like synaptic and cognitive impairment induced by Aβ1–42 oligomers." (PMID 32670047, 2020). "Moreover, we found that CaSR also mediated Aβ1–42-induced cognitive deficits." (PMID 32670047, 2020).
cystitis (1 paper, 2021). Inflammation of the urinary bladder. "Furthermore, we evaluated the effect of the CaSR on cystitis-induced bladder hyperactivity." (PMID 34681183, 2021).
diabetes insipidus (1 paper, 2025). A disorder characterized by excretion of large amounts of urine, accompanied by excessive thirst. "Concurrent CaSR activation in the distal convoluted tubules suppresses aquaporin-2 expression, inducing nephrogenic diabetes insipidus and further reducing water reabsorption." (PMID 41141160, 2025).
disc degeneration (1 paper, 2023). "However, calcium-induced disc degeneration can be reversed through co-culturing with cells using calcium-sensitive receptor (CaSR) antagonists or by suppressing the expression of CaSR." (PMID 38068915, 2023).
endocarditis (1 paper, 2023). Inflammation of the endocardium. "However, further research is necessary to comprehensively elucidate the relationship between CaSR and endocarditis." (PMID 37510130, 2023). "Therefore, modulating the activity of CaSR may have therapeutic potential for treating endocarditis." (PMID 37510130, 2023).
endometrial cancer (1 paper, 2018). Primary or metastatic malignant neoplasm involving the endometrium (mucous membrane that lines the endometrial cavity). "Reduced CaSR was evident in endometrial cancer relative to the normal specimen and was associated with multiple clinicopathological characteristics, including histologic grade, myometrial invasion, lymph node metastasis and E-cadherin and VEGFR3 expression." (PMID 29348629, 2018). "The purpose of this study was to characterize the role of CaSR in endometrial cancer and to understand the underlying mechanisms behind CaSR-mediated regulation of apoptosis, invasion and metastasis with the goal of uncovering a new anticancer target for endometrial cancer." (PMID 29348629, 2018). "This study is the first to explore the role of CaSR in endometrial cancer, and further investigations are warranted to clarify the precise mechanism of its inhibitory effect." (PMID 29348629, 2018). "Our results showed clear CaSR expression in an endometrial cancer cell line and decreased expression in endometrial cancer specimens." (PMID 29348629, 2018). "Our study is also the first to prove that CaSR is expressed in endometrial cancer where it induces apoptosis." (PMID 29348629, 2018). "In this study, we highlighted calcium as a promising factor in the effort to induce apoptosis that was dependent (at least in part) on CaSR expression in endometrial cancer cells." (PMID 29348629, 2018). "Furthermore, CaSR expression in endometrial cancer specimens was negatively correlated with VEGFR3 (R2 = 0.255, P < 0.001)." (PMID 29348629, 2018). "CaSR activation may suppress lymphangiogenesis in endometrial cancer by restraining VEGFR3 expression, though further evidence is needed." (PMID 29348629, 2018). "The precise mechanism and therapeutic potential of CaSR in endometrial cancer remains unexplored." (PMID 29348629, 2018). "This study provides a preliminary analysis of the CaSR effect on endometrial cancer development." (PMID 29348629, 2018). "VEGFR3, which is inversely correlated with CaSR, is elevated in endometrial cancer." (PMID 29348629, 2018). "Additionally, an immunohistochemical analysis showed that VEGFR3 was significantly increased in endometrial cancer compared with the normal endometrium and was inversely correlated with CaSR expression." (PMID 29348629, 2018). "Moreover, a reduction in CaSR expression in endometrial cancer relative to normal specimens was evident by immunohistochemistry and was positively associated with E-cadherin, but not β-catenin, expression." (PMID 29348629, 2018). "Additionally, activated CaSR facilitates E-cadherin/β-catenin complex formation at the cell membranes of endometrial cancer cells to potentially inhibit tumour invasion." (PMID 29348629, 2018). "Therefore, reduced CaSR expression may be a suitable explanation and valuable predictor for endometrial cancer progression." (PMID 29348629, 2018). "Thus, it is worth pursuing whether an adjuvant therapeutic approach for endometrial cancer can be developed based on the regulation of calcium metabolism or by specifically targeting CaSR." (PMID 29348629, 2018). "Thus, CaSR may inhibit VEGFR3 expression in endometrial cancer." (PMID 29348629, 2018). "Ectopic CaSR expression inhibited invasion, stabilized adhesion, and led to more E-cadherin/β-catenin complexes; it also decreased VEGFR3 expression in an endometrial cancer cell line." (PMID 29348629, 2018). "However, the role of CaSR in endometrial cancer remains unknown." (PMID 29348629, 2018). "Moreover, excessive CaSR expression contributed towards attenuating cell proliferation, invasion, cell adhesions and VEGFR3 in endometrial cancer." (PMID 29348629, 2018). "However, there are no published studies on the role of CaSR in endometrial cancer." (PMID 29348629, 2018).
endometrial tumours (1 paper, 2018). "The role of CaSR in the intercellular adherens junctions of endometrial tumours remains unclear." (PMID 29348629, 2018).
endothelial dysfunction (1 paper, 2026). In vascular diseases, endothelial dysfunction is a systemic pathological state of the endothelium (the inner lining of blood vessels) and can be broadly defined as an imbalance between vasodilating and vasoconstricting substances produced by (or acting on) the endothelium. "In non-septic models, CaSR activation was associated with tissue and organ injury, including renal and cardiac damage, as well as vasoplegia related to endothelial dysfunction." (PMID 41998370, 2026).
energy metabolism disorder (1 paper, 2017). "Obviously, the downregulation of CaSR expression is a critical mechanism leading to energy metabolism disorder induced by HG." (PMID 28518143, 2017). "In present study, by using high glucose (HG)-induced energy metabolism disorder model in the primary cultured cardiomyocytes, we studied the effect of CaSR in maintaining ATP content and protecting the structure and function of mitochondria and gap junction." (PMID 28518143, 2017).
erectile dysfunction (1 paper, 2020). Persistent or recurrent inability to achieve or to maintain an erection during sexual activity. "Therefore, the CaSR/PLC/PKC signaling pathway may play a crucial role in the erectile dysfunction associated with streptozotocin-induced diabetic rats." (PMID 31922200, 2020).
esophageal cancer (1 paper, 2024). A primary or metastatic malignant neoplasm involving the esophagus. "Currently, it remains uncertain whether CaSR influences the proliferation and differentiation of cancer cells in esophageal cancer." (PMID 38920679, 2024).
familial hypoparathyroidism (1 paper, 2024). A rare heterogeneous group of metabolic disorders characterized by abnormal calcium metabolism due to deficient secretion of parathormone (PTH), without other endocrine disorders or developmental defects. "Testing for mutations in genes associated with familial hypoparathyroidism, such as CaSR, GCM2, or PTH, should be considered to rule out an inherited etiology." (PMID 39416579, 2024).
gestational diabetes mellitus (1 paper, 2016). "Reduced expression of CaSR in placentas derived from women suffering from gestational diabetes mellitus compared with healthy placentas was found." (PMID 27625611, 2016).
glomerulosclerosis (1 paper, 2021). A hardening of the kidney glomerulus caused by scarring of the blood vessels. "Stimulation of the calcium-sensing receptor constitutes a new approach to stabilize podocyte cytoskeleton, improves cell survival, and reduces glomerulosclerosis." (PMID 33606151, 2021).
glucosuria (1 paper, 2025). "Other possible mechanisms include increased activity of the thiazide-sensitive sodium chloride cotransporter on the distal convoluted tubule by allosteric modification of calcium-sensing receptor (CaSR), which is significantly activated by glucosuria induced by SGLT2 inhibition." (PMID 39937358, 2025).
Graves disease (1 paper, 2017). Graves' disease is an autoimmune disorder that leads to overactivity of the thyroid gland (hyperthyroidism).It is caused by an abnormal immune system response that causes the thyroid gland to produce too much thyroid hormones. "Previous studies have investigated a putative autoimmune etiology for pHPT, including identification of antibodies targeting CASR in analogy with Graves’ disease." (PMID 28855268, 2017).
growth disorders (1 paper, 2023). "All these variants were identified in genes already associated with growth disorders: PROKR2 (N = 2), PTPN11 (N = 6), ANKRD11 (N = 1), NPR2 (N = 1), NF1 (N = 1), ACAN (N = 1), GH1 (N = 1), FBN1 (N = 1), COMP (N = 1), IGF1R (N = 1), ARID1A (N = 1), and CASR (N = 1)." (PMID 37605180, 2023).
Hearing impairment (1 paper, 2019). A decreased magnitude of the sensory perception of sound. "One possibility for this hearing impairment is the inhibition of CaSR signaling, which suppresses the entry of extracellular calcium into the connective tissue system as suggested by the results of imaging." (PMID 31379498, 2019).
hepatocellular carcinoma (1 paper, 2022). A malignant tumor that arises from hepatocytes. "In line with their report, we also demonstrated that spermine stimulation activates CaSR, which in turn mediates Ca2+ entry to increase [Ca2+]cyt and consequent activation of Akt and β-catenin in hepatocellular carcinoma cells." (PMID 36348350, 2022).
hyperhomocysteinemia (1 paper, 2021). A serious metabolic condition caused by mutations in the MTHFR gene, medications, or nutritional deficiency. "CaSR activation has been shown to counteract activation of blood platelets in hyperhomocysteinemia." (PMID 33804889, 2021). "At least in theory, inhibition of ORAI and STIM expression and SOCE could contribute to the previously observed inhibition of platelet activity by CaSR activation in hyperhomocysteinemia." (PMID 33804889, 2021).
Hypernatremia (1 paper, 2023). An abnormally increased sodium concentration in the blood. "For our protocol we relied on an adapted version using metabolic alkalosis, hypernatremia and correctedAlb Ca levels and excluding the CaSR." (PMID 38127207, 2023).
Hypoinsulinemia (1 paper, 2017). A decreased concentration of insulin in the blood. "Mice with a germline gain-of-function CaSR mutation have hypoinsulinemia, hyperglucagonemia, reduced pancreatic islet mass, and impaired glucose tolerance, which is rectifiable by calcilytic therapy." (PMID 28575322, 2017). "Thus, Nuf mice with a gain-of-function CaSR mutation exhibited impaired glucose tolerance, which was associated with reduced pancreatic islet mass and hypoinsulinemia as well as a lack of glucose-mediated suppression of glucagon secretion." (PMID 28575322, 2017).
interstitial cystitis (1 paper, 2021). A rare chronic debilitating urogenital disease characterized by urinary frequency, urgency, and pelvic pain. "Therefore, we examined the effects of CaSR agonist on interstitial cystitis-induced bladder hyperactivity caused by cyclophosphamide (CYP)." (PMID 34681183, 2021).
intestinal neuroendocrine tumor (1 paper, 2022). "γ-[Glu](n = 1,2)-Phe/-Met/-Val upregulated the activation of CaSR and engendered Ca2+ mobilization, leading to GLP-1 release from intestinal neuroendocrine tumor STC-1 cells." (PMID 35737050, 2022).
intrahepatic cholestasis (1 paper, 2020). A cholestasis characterized by impairment of the bile flow caused by obstruction located in the liver. "Collectively, LDHJ granules functions as an antagonist of CaSR to restrain cell apoptosis by inhibiting the mitochondrial pathway in intrahepatic cholestasis models." (PMID 32180721, 2020).
invasive breast carcinoma (1 paper, 2023). A carcinoma that infiltrates the breast parenchyma. "In our study, which was a retrospective analysis of 79 patients with NST invasive breast cancer, the CaSR was found to be a relevant marker of tumor size and aggressiveness, irrespective of the tumor surrogate subtype." (PMID 37511437, 2023).
jaw cysts (1 paper, 2023). "Our results are in line with other studies that demonstrated increased PGE2 production after CaSR stimulation in neurons, dental pulp cells, and fibroblasts from jaw cysts and gingiva." (PMID 37153788, 2023).
lactose intolerance (1 paper, 2008). "We examined genetic polymorphisms that might influence calcium metabolism: lactase (LCT) gene 13910 C/T polymorphism causing lactose intolerance and calcium-sensing receptor (CaSR) gene A986S polymorphism as a responsible factor for the altered cellular calcium sensation." (PMID 18980667, 2008).
lentivirus infection (1 paper, 2018). Virus diseases caused by the Lentivirus genus. "Finally, in order to further elucidate the molecular mechanism by which CaSR contributes to cardiac injury induced by Iso, we established a gain-of-function mutation in CaSR by lentivirus infection." (PMID 30364197, 2018). "As we expected, CaSR activation by lentivirus infection resulted in CaSR upregulation, [Ca2+]i overload, and CaMKII and CaN pathway activation as well as cardiomyocyte hypertrophy and apoptosis." (PMID 30364197, 2018). "Finally, to confirm the regulatory effect of CaSR on the CaMKII and CaN pathways induced by Iso, we upregulated CaSR expression through lentivirus infection." (PMID 30364197, 2018).
leukaemia (1 paper, 2023). "Our studies suggest CaSR to be a differential and targetable factor in leukaemia progression influencing self-renewal of AML LSC via [eCa2+] cues from the BMM." (PMID 37802982, 2023). "Consistently, MLL-AF9+ CaSR KO AML cells, exhibited a reduced percentage of Gr1 low cells, while CaSR OE leukaemia cells were characterised by a higher percentage of this blast-enriched Gr1 low population." (PMID 37802982, 2023). "As shown in multiple in vitro and in vivo models, CaSR and its downstream signalling play a crucial and differential role in various leukaemia types, contributing to disease progression and self-renewal capabilities of LSC in AML." (PMID 37802982, 2023). "On human leukaemia cells, the percentage of CaSR+ cells was highest in MLL-AF9+ THP1 (AML) cells compared to AML cells expressing a different oncoprotein (Kasumi), NALM-6 (B-ALL) or K562 (CML) cells (P < 0.0001)." (PMID 37802982, 2023). "CaSR-associated differences between MLL-AF9+ and BCR-ABL1+ leukaemias in our study may be due to the observed higher levels of CaSR-pERK in MLL-AF9+ cells at baseline." (PMID 37802982, 2023). "Furthermore, our results on the highly context-specific role of CaSR for leukaemia development is supported by published reports on the tumour suppressive versus oncogenic function of CaSR11,13." (PMID 37802982, 2023). "In summary, these findings indicate that CaSR plays a highly oncogene- and/or disease-specific, differential role in CML, B-ALL and AML affecting pathophysiological features in leukaemia cells." (PMID 37802982, 2023). "Our data suggest that CaSR signalling is an important determinant of AML LSC stemness and leukaemia progression, but in how far niche location and [eCa2+] in the BMM may interplay or even synergise, will need to be determined." (PMID 37802982, 2023).
Leydig cell tumor (1 paper, 2016). A sex cord-stromal tumor occurring in the testis and rarely in the ovary. "While CaSR expression in normal rat Leydig cells could not be shown, cultured Rice H-500 rat Leydig cell tumor express the receptor mRNA and protein." (PMID 27625611, 2016).
lipid metabolism disorders (1 paper, 2022). "Finally, a lipidomics approach was applied to reveal the regulation of CASR on lipid metabolism disorders in CHD." (PMID 36016561, 2022). "Finally, a lipidomics approach was applied to explore the different lipid metabolites to verify the regulation of CASR on lipid metabolism disorders in CHD." (PMID 36016561, 2022).